IL36G (interleukin 36 gamma)
Description:
Cytokine that binds to and signals through the IL1RL2/IL-36R receptor which in turn activates NF-kappa-B and MAPK signaling pathways in target cells. Part of the IL-36 signaling system that is thought to be present in epithelial barriers and to take part in local inflammatory response; similar to the IL-1 system with which it shares the coreceptor IL1RAP. Seems to be involved in skin inflammatory response by acting on keratinocytes, dendritic cells and indirectly on T-cells to drive tissue infiltration, cell maturation and cell proliferation. In cultured keratinocytes induces the expression of macrophage, T-cell, and neutrophil chemokines, such as CCL3, CCL4, CCL5, CCL2, CCL17, CCL22, CL20, CCL5, CCL2, CCL17, CCL22, CXCL8, CCL20 and CXCL1; also stimulates its own expression and that of the prototypic cutaneous pro-inflammatory parameters TNF, S100A7/psoriasin and inducible NOS. May play a role in pro-inflammatory responses during particular neutrophilic airway inflammation: activates mitogen-activated protein kinases and NF-kappa B in primary lung fibroblasts, and stimulates the expression of IL-8 and CXCL3 and Th17 chemokine CCL20 in lung fibroblasts. May be involved in the innate immune response to fungal pathogens, such as Aspergillus fumigatus.
Synonyms: IL-1RP2; IL-1F9; IL-1H1; IL1E; IL1F9; IL1H1; IL1RP2
Tractability: Small molecule: a structure with a bound ligand is known. Antibody: UniProt places it where antibodies can reach, with high confidence; its Gene Ontology location is reachable by antibodies, with high confidence.
Target class: Secreted protein
Gene: Protein-coding gene on chromosome 2 (112,973,203 to 112,985,658, forward strand). Ensembl gene ENSG00000136688.
Subcellular location: Cytoplasm; Secreted
Subcellular location (Human Protein Atlas): Cytosol; Nucleoplasm; Plasma membrane; Predicted to be secreted
Pathways (Reactome):
Immune System: Interleukin-36 pathway
Gene Ontology:
Molecular function: cytokine activity; interleukin-1 receptor binding
Biological process: cell-cell signaling; cellular response to lipopolysaccharide; cytokine-mediated signaling pathway; immune response; inflammatory response
Cellular component: cytoplasm; cytosol; extracellular region
Genetic constraint (gnomAD): Loss-of-function variants: 5 observed, 8.49 expected, observed/expected ratio (o/e) 0.59, 90% interval 0.31 to 1.24. That is too few expected variants to judge how well the gene tolerates losing a copy. Missense variants: 150 observed, 168.36 expected, observed/expected ratio (o/e) 0.89, 90% interval 0.78 to 1.02. Synonymous variants: 70 observed, 63.37 expected, observed/expected ratio (o/e) 1.1, 90% interval 0.91 to 1.35.
Homologues: Orthologues: chimpanzee IL36G (99% identical), macaque IL36G (89% identical), rabbit IL36G (62% identical), rat Il36g (54% identical), mouse Il36g (53% identical), zebrafish il1b (22% identical), zebrafish il1fma (19% identical). Paralogues in human: IL36A (52% identical), IL36B (40% identical), IL37 (33% identical), IL1RN (27% identical), IL36RN (26% identical), IL1B (25% identical), IL1F10 (24% identical).
Diseases named in the same sentence as IL36G in open-access papers:
IL36G is named in the same sentence as 47 diseases in open-access papers, as found by Europe PMC text mining. Sharing a sentence is not in itself a finding about the gene and the disease. The quoted sentences say what the papers report.
psoriasis (50 papers, 2010 to 2025). An autoimmune condition characterized by red, well-delineated plaques with silvery scales that are usually on the extensor surfaces and scalp. "Simultaneously, IDMF represses pro-inflammatory transcription factors, including NF-κB, AP-1, and potentially IRF1, leading to the downregulation of key psoriasis-associated cytokines such as IL-17A, IL-23A, IL-36G, and IFN-γ." (PMID 41465291, 2025). "The co-expression of AVP genes and IL36G was associated with psoriasis severity and therapeutic efficacy." (PMID 36172384, 2022). "Since IL36G has previously demonstrated markedly increased levels in plaque psoriasis patients and is linked to IL-23/IL-17 axis critical in psoriasis pathology, it was chosen to be the focus of current report." (PMID 30634937, 2019). "More precisely, IL36G was recently identified as one of the 13 hallmark psoriasis genes universally or near-universally up-regulated in psoriasis lesions." (PMID 25897967, 2015). "Immune-related genes (e.g. CCL8, LCP2, CD1E) and IL-36G, which was recently associated with psoriasis pathogenesis, were increased in AD LS skin." (PMID 26459294, 2015). "Molecular analysis of the skin of IgG- and anti-IL36R-treated K14-IL17Aind mice revealed effective suppression of psoriasis-associated cytokines (Il36a, Il36g, Il36b, Il23a, and Tnf), chemokines (Cxcl1, Cxcl5, and Ccl2) and antimicrobial-peptides (such as Defb4) on mRNA level." (PMID 38162658, 2023). "Although gaps in our understanding of these relationships remain, our working hypothesis is that PCSK9 SNP rs662145 C > T may predispose individuals to psoriasis by increasing baseline cutaneous expression of IL36G." (PMID 35862195, 2022). "It is notable that in a large scale meta-analysis of skin samples from 237 psoriasis patients, the gene encoding IL-36G (IL36G) was 1 of only 5 genes with elevated expression in lesional skin from all 237 patients, indicating that elevated IL36G expression is a near-universal feature of PsV lesions." (PMID 29434599, 2018). "For instance, IL-36γ, IL-1F9 have been proposed as markers to differentiate AD from psoriasis, as their expression is significantly elevated in the skin lesions of patients with psoriasis." (PMID 40725743, 2025). "In psoriasis, IL‐36G is primarily found in keratinocytes and is also expressed in infiltrating monocytes." (PMID 40159643, 2025). "IL36G‐expressing monocytes serve as a common biomarker for ad and psoriasis and can also be used as a distinguishing target between ad and urticaria." (PMID 40159643, 2025). "We identified five cytokines and receptors that intersected between urticaria, atopic dermatitis, and psoriasis: IL36G, IL20, IL1B, CXCR1, and CXCL1." (PMID 40159643, 2025). "Our study highlights IL36G‐expressing monocytes as a common key target in atopic dermatitis and psoriasis, offering novel insights and therapeutic strategies for these related diseases." (PMID 40159643, 2025). "This study, based on bioinformatics and immune infiltration analysis, identified IL36G‐expressing monocytes as a critical target in atopic dermatitis (ad) and an important player in psoriasis." (PMID 40159643, 2025). "In parallel, IDMF suppresses NF-κB, AP-1, IRF1, and STAT-linked pathways, thereby downregulating IL-17A, IL-23A, IL-36G, IFN-γ, and other psoriasis-associated cytokines at their transcriptional origins." (PMID 41465291, 2025). "IL36G‐expressing monocytes are specifically expressed in both psoriasis and ad, and they can serve as a distinguishing target between urticaria and ad, two type 2 inflammatory skin diseases." (PMID 40159643, 2025). "We performed molecular docking of clinical drugs and IL‐36G using three different therapeutic drugs for atopic dermatitis and psoriasis to verify IL‐36G as a key target for treating these conditions." (PMID 40159643, 2025). "Several genes exemplified this scenario such as IL36G and IL36RN associated with psoriasis, and CSF3 associated with severe neutropenia." (PMID 40208878, 2025).
psoriasis (continued). "Further analysis revealed that IL‐36G‐expressing monocytes are highly expressed in psoriasis, indicating their potential as a shared therapeutic target for both atopic dermatitis and psoriasis." (PMID 40159643, 2025). "qPCR analysis showed that the psoriasis-associated genes IL17C, LL37, and IL36G (respectively) were induced upon stimulation with PMA NETs." (PMID 38783164, 2024). "It induces the expression of other psoriasis signature genes, such as IL36G, S100A15, DEFB4A, S100A9, CXCL8, TNIP3 (coding TNF-α-induced-protein 3 or TNFAIP3), and LCN2 (by synergy of IL-17C with TNF-α) in keratinocytes." (PMID 36928592, 2023). "The core NB-UVB downregulated DEGs included a few psoriasis signature genes, such as IL36G, DEFB4A/B (coding human β defensin 2), S100A15, SERPINB4, KRT16, KRT6A, and DSC220." (PMID 36928592, 2023). "In conclusion, NB-UVB normalizes psoriatic plaques by suppressing the expression of psoriasis signature genes, such as IL36G, DEFB4A/B, S100A15, SERPINB4, KRT16, and KRT6A in, both, the PE and CE skin." (PMID 36928592, 2023). "A recent study reported that NFKBIZ was co-expressed with IL36G in the stratum spinosum of psoriasis epidermis." (PMID 35563374, 2022). "There are 122 differentially upregulated and 210 differentially downregulated genes in common between the activated + fisetin and the activated group alone, notably many psoriasis-associated genes such as CCL20, IL36G, IL23A and NFKBIZ." (PMID 36741386, 2022). "The top 25 most common DEGs in the suprabasal keratinocytes between GSE151177 and GSE162183 both included IL36G, a keratinocyte-derived cytokine known as an important factor in psoriasis pathogenesis." (PMID 35693818, 2022). "IL36G is a pro-inflammatory cytokine whose role in the pathogenesis of psoriasis has been extensively described." (PMID 36172384, 2022). "For the differentiation of AD and psoriasis, studies have shown that the expression of interleukin (IL)-36γ (IL-1F9) in the skin lesions of patients with psoriasis is significantly increased, which can be used to distinguish between AD and psoriasis." (PMID 36465933, 2022). "We identified IL-17 as the main Th17 cell derived cytokine that induced upregulation of the genes encoding NF-kappa-B inhibitor zeta (NFKBIZ) and psoriasis-associated mediators, including CCL20, IL36G, and the antimicrobial peptide human β Defensin 2 (DEFB4A)." (PMID 30972071, 2019). "We can consider the activation of IL36G as the most significant finding and propose the family of these genes to be important biomarkers for psoriasis." (PMID 25897967, 2015). "Moreover, differential gene expression analysis between atopic dermatitis and psoriasis demonstrated higher levels of IL‐36G and monocytes in psoriasis." (PMID 40159643, 2025). "Through immune cell‐related analysis, we found that IL36G‐expressing monocytes may be a common target in both atopic dermatitis and psoriasis." (PMID 40159643, 2025). "In summary, our study establishes PCSK9 as a possible psoriasis-susceptibility locus and demonstrates its negative relationship with IL36G at the gene expression and protein levels." (PMID 35862195, 2022). "In order to explore the association between the AVPs and IL36G expression levels in the context of psoriasis severity, we further investigated the relationship between levels of AVPs and IL36G and Psoriasis Area Severity Index (PASI) scores during psoriasis treatment." (PMID 36172384, 2022). "Whether upregulation of IL36G and AVPs expression in keratinocytes trigger psoriasis is currently unknown." (PMID 36172384, 2022). "We then investigated whether PCSK9 is linked to other potential inflammatory mediators of psoriasis in addition to IL36B and IL36G." (PMID 35862195, 2022).
psoriasis (continued). "For example, a recent study focused on the evaluation of a variety of datasets from transcriptomic studies including several forms of psoriasis, atopic dermatitis, lichen planus, and contact dermatitis to train a classifier using four genes only (IL36G, CCL27, NOS2, C10ORF99)." (PMID 31973112, 2020). "Scratch injury upregulates the gene expression of CCL20, CXCL8, and IL36G, which may be related to the scratch-induced Koebner phenomenon frequently observed in patients with psoriasis." (PMID 32070069, 2020). "Moreover, IL-17A upregulates IL-36G production more potently in human psoriasis-derived keratinocytes than in healthy keratinocytes." (PMID 32070069, 2020). "IL36B and IL36G are both in the core set of DEGs and highly up-regulated in each form of psoriasis." (PMID 30054515, 2018). "Finally, we examined the correlation and expression of these cytokines and their related receptors in immune cells, discovering that monocytes had the highest positive correlation with these genes, with IL‐36G‐expressing monocytes also showing high expression in psoriasis." (PMID 40159643, 2025). "IL36G and antiviral proteins may be closely related with the pathogenesis of psoriasis, and they may represent new candidate molecular markers for the occurrence and severity of psoriasis." (PMID 36172384, 2022). "Indeed, one recent study identified IL36G as the most outstanding biomarker for psoriasis." (PMID 25897967, 2015). "IL36G was also highly expressed in psoriasis, and correlation analysis indicated that IL36G was closely related to IL36A, IL19, CXCL1, and CXCL8, all of which participate in the pathogenesis of psoriasis." (PMID 40159643, 2025). "The downregulated genes detected at day 14 in these populations included inflammatory molecules (e.g., IL36G, S100A7/A8/A9) and structural proteins (GJB2, KRT16/17), known to be over-expressed in the upper layers of the psoriasis epidermis." (PMID 38291032, 2024). "After systemic IL-17A blockade, the expression of those inflammatory mediators (IL36G, S100A8, DEFB4A, and DEFB4B) was decreased in posttreatment psoriasis lesional skin KCs compared to pretreatment psoriasis lesional skin KCs (p < 0.05)." (PMID 37781383, 2023). "The number of IL36G and/or DEFB4A expressing KCs in S. corneum and S. granulosum was decreased by 3 times from pretreatment psoriasis lesional skin to posttreatment psoriasis lesional skin." (PMID 37781383, 2023). "After IL-17A blockade, KC expression of IL36G, S100A8, DEFB4A, and DEFB4B in S. corneum and S. granulosum decreased in posttreatment psoriasis lesional skin compared to pretreatment psoriasis lesional skin (p < 0.05)." (PMID 37781383, 2023). "The expression of inflammatory mediators induced by IL-17 in keratinocytes (IL36G, S100A8, DEFB4A, and DEFB4B) was increased in pretreatment psoriasis lesional skin KCs compared to control skin KCs (p < 0.05)." (PMID 37781383, 2023). "The expression of IL-17-driven inflammatory mediators (IL36G, S100A8, DEFB4A, and DEFB4B) in suprabasal keratinocytes was correlated with psoriasis severity and was downregulated by IL-17A blockade." (PMID 37781383, 2023). "In psoriasis patients receiving anti‐IL‐17A treatment, expression of NFKBIZ and IL36G are positively correlated." (PMID 36245291, 2022). "For example, intrinsic AD in contrast to extrinsic AD showed upregulation of psoriasis-typical genes (e.g., IL22, IL36G, CCL19, and CCL22) complicating discrimination of intrinsic AD and psoriasis." (PMID 31973112, 2020). "Results from qRT-PCR measurements of psoriasis-relevant transcripts showed that levels of DEFB4B, IL36G, LCN2, S100A7, S100A8 mRNA were significantly decreased in rhodomyrtone-treated cultures when compared with cytokine-treated cultures (p<0.0001, all)." (PMID 30321197, 2018). "The analysis revealed that IL36G‐expressing monocytes were also highly expressed in psoriasis but did not play a pivotal role in urticaria." (PMID 40159643, 2025).
psoriasis (continued). "This study identified IL36G‐expressing monocytes as a potential target for ad and demonstrated through immune infiltration analysis that ad shares similarities with psoriasis rather than urticaria." (PMID 40159643, 2025). "We revealed 479 differentially expressed genes between secukinumab and Dead Sea climatotherapy at the end of treatment, with a psoriasis panel identifying SERPINB4, SERPINB13, IL36G, IL36RN, and AKR1B10 as upregulated in Dead Sea climatotherapy compared with secukinumab." (PMID 38892277, 2024). "When we compared KC transcriptome in different epidermal layers, the expression of IL-17-driven inflammatory mediators (IL36G, S100A8, DEFB4A, and DEFB4B) was localized to suprabasal layers (S. corneum, S. granulosum, and S. spinosum) in pretreatment psoriasis lesional skin." (PMID 37781383, 2023). "In addition, some of these core NB-UVB-downregulated DEGs, such as IL36G and DEFB4A/B, were involved in IL-6 and IL-17 signaling, which are key cytokines in psoriasis pathogenesis." (PMID 36928592, 2023). "Furthermore, successful treatment of psoriasis with the anti-psoriatic standard treatment etanercept is accompanied by a decrease in IL36A, IL36G and IL36RN expression." (PMID 32484435, 2020). "RNA-seq data from NHK treated with TNF and rhodomyrtone confirmed the inhibitory effect of rhodomyrtone, particularly on the IL-17A/TNF induction of DEFB4, IL36G, and CXCL1, all known to be highly expressed in psoriasis lesions and investigated as potential biomarkers." (PMID 30321197, 2018). "In our study we only found IL36 cytokines (IL36G, IL36RN and IL36A) to be related to psoriasis." (PMID 25897967, 2015). "In addition, IL-36G upregulates the expression of CCN1 and S100A7A, leading to the production of excessive pro-inflammatory factors by the cells, including IL-1, IL-6, IL-8, IL-36, and TNF, which promotes psoriasis." (PMID 40735322, 2025). "Furthermore, we found that the expression levels of IL36G and the 4 AVPs showed positive correlation with PASI score in patients with psoriasis, and that these levels decreased significantly during treatment with biological therapies, but not with methotrexate." (PMID 36172384, 2022). "However, the exact production mechanism of IL36G and AVPs, and the regulatory relationship between them in the context of psoriasis, have still not been sufficiently investigated." (PMID 36172384, 2022). "Recapitulating psoriasis skin, IL-17A+TNF-α treatment lead to increased expression of DEFB4, PI3, LCN2, S100A7, and IL36G mRNA over a 72 h time course without marked deterioration of tissue structure." (PMID 30321197, 2018). "Most well known psoriasis related genes activated in non-lesional skin are IL6, IL22, IL36A, IL36G, IL19, IL20, S100A7 and S100A12." (PMID 25897967, 2015).
psoriasis vulgaris (4 papers, 2019 to 2023). Plaque psoriasis is the most common presentation of psoriasis. "IL-36 receptor expression (encoded by IL1RL2), as well as the expression of IL36A, IL36B, and IL36G are significantly upregulated in psoriasis vulgaris skin lesions, compared to healthy and non-lesional skin samples." (PMID 38162658, 2023). "In summary, we demonstrated that the presence of IL36G may mediate the keratinocyte expression of AVPs such as MX1, ISG15, IFI27, and IFI44L in psoriasis vulgaris." (PMID 36172384, 2022).
colitis (3 papers, 2022 to 2025). Inflammation of the colon. "Hematoxylin and eosin (HE) and Masson's trichrome staining of the colons showed less leukocyte infiltration, muscle fibers and collagen, and more intact epithelium in the colon from Il1f9−/− mice than Il1f9+/+ mice, suggesting a proinflammatory role of IL‐36γ in DSS‐induced colitis." (PMID 35119210, 2022).
inflammatory skin disease (3 papers, 2016 to 2025). Inflammatory skin disorders covers a broad category that includes many conditions ranging in severity, from mild itching to grave medical health complications These disorders are common in people of all ages and races. "We analysed the role of IL‐36G and monocytes in inflammatory skin diseases clinically similar to ad." (PMID 40159643, 2025). "This suggests that they may exert their effects by inhibiting IL36G, thereby supporting the feasibility of targeting IL36G in inflammatory skin diseases." (PMID 40159643, 2025).
viral infection (3 papers, 2017 to 2022). "In our study, we observed higher concentrations of IL-36γ in plasma and elevated mRNA levels of IL-36G and IL-36R in influenza-induced ARDS patients, suggesting its potential association with viral infection." (PMID 33193319, 2020). "Previous research has suggested that IL36G may be an alarmin that signals viral infection." (PMID 36172384, 2022).